GSK3B (glycogen synthase kinase 3 beta)
Diseases named in the same sentence as GSK3B in open-access papers (continued):
Sharing a sentence is not in itself a finding about the gene and the disease.
cancer (continued). "GSK3β has been linked totumorigenesis and the development of cancer as formallyestablished by in vitro and in vivo experiments when dys-regulated." (PMID 31354196, 2019). "It has been reported that GSK-3β is linked to poor prognostic/cancer progression and that the inhibition of GSK-3β suppresses tumorigenesis by attenuating cell proliferation, while increasing apoptosis and restraining cell motility." (PMID 31466222, 2019). "This blockade was associated with a transcriptional repression of genes important for cell cycle progression, metabolism and poor prognosis in cancer patients, including cMYC, GSK3-β and mutated p5340,48,49." (PMID 30862884, 2019). "The Has2-deficient Has2Δ/Δ cancer cells displayed greatly reduced Akt phosphorylation at both Ser473 and Thr308 as well as GSK3β phosphorylation at Ser9 as compared with control Has2flox/flox cells." (PMID 31645543, 2019). "In accordance with the reduced phosphorylation of GSK3β, the expression of β-catenin was decreased in Has2-deficient Has2Δ/Δ cancer cells." (PMID 31645543, 2019). "Glycogen synthase kinase-3 beta (GSK-3β), a serine/threonine protein kinase that has been extensively implicated in critical cell biology processes, is a promising multipurpose kinase for cancer therapeutic target." (PMID 29786660, 2018). "GSK-3β has been implicated in playing a role in cancers which are resistant to chemo-, radio-, and targeted therapy." (PMID 29561817, 2018). "Overexpression of phosphorylated GSK3β serine 9, coupled with active β-catenin, has been associated with poor prognosis in various cancers." (PMID 29371979, 2017). "In cancer, GSK3β has been implicated in development and progression of breast, brain, pancreatic, colon and prostate tumours, although it displays disparate activity in differing tissues and tumour types." (PMID 27907888, 2017). "Gsk3-β has a significant role in the wnt signalling pathway, which is directly associated with the pro-tumorigenic and metastatic development in several cancer types." (PMID 28926938, 2017). "Compared to the controls, tumors in mice treated with GSK-3β inhibitors consisted of fibroblast-like cancer cells and were associated with reactive stromal and inflammatory cells." (PMID 27780915, 2016). "Altered GSK3β expression is associated with numerous pathological processes, including type 2 diabetes, Alzheimer’s disease, and cancer." (PMID 26213494, 2015). "Recombinant capsid protein VP1 (rVP1) of foot-and-mouth disease virus binds to integrins to modulate Akt/GSK3-β signaling and suppress migration/invasion and metastasis of cancer cells, but the underlying molecular mechanism is unclear." (PMID 25004182, 2014). "Melatonin is responsible for activating GSK3β, which in turn inhibits epithelial-to-mesenchymal transition, a critical process in underlying cancer spread and metastasis." (PMID 24319459, 2013). "Glycogen synthase kinase 3β (GSK3β) regulates multiple cellular pathways and is implicated in various diseases including cancer." (PMID 23408967, 2013). "The expression of β-catenin is rather low in non-cancer cells as GSK-3β causes its phosphorylation and consequent degradation by the ubiquitin-proteasome pathway." (PMID 20537156, 2010). "Deregulation of GSK3β activity is implicated in the pathogenesis of neurodegenerative and metabolic disorders, but also in cancer." (PMID 20352103, 2010). "GSK3β outperformed GSK3α as a pan-cancer diagnostic biomarker, achieving superior AUC in 9 tumors." (PMID 41915675, 2026). "As GSK3β is implicated in various physiological and pathological processes, understanding its multifaceted roles can lead to novel therapeutic strategies for neurodegenerative diseases, cancer and other conditions." (PMID 41190025, 2025). "The PI3K/Akt/GSK-3β pathway is a significant cause of chemoresistance in cancer therapy." (PMID 40506749, 2025).
cancer (continued). "Importantly, genetic and pharmacological destruction of GSK3B-mediated T334 phosphorylation leads to HR repair deficiency and makes cancer cells susceptible to synthetic lethality of PARPi therapy independent of BRCA1 status." (PMID 41243969, 2025). "Alternatively, targeting downstream effectors of GSK3β may have less adverse effects, potentially circumventing the risk of cancer." (PMID 39392548, 2025). "Dysregulation of GSK-3β signaling is implicated in various diseases, including cancer." (PMID 38756274, 2024). "Upon GSK3β inhibition, nuclear p38α phosphorylates β-catenin at residues S111 and T112, allowing its binding to promoter regions of Wnt target genes and the activation of a transcriptional program implicated in cancer progression." (PMID 38041178, 2023). "Moreover, cancer progression and the chemoresistance of PDACs have been associated with elevated histone deacetylases (HDACs) and glycogen synthase kinase 3 beta (GSK3B) activity." (PMID 37444617, 2023). "In the present study, we explored computational simulations through bioinformatics analysis and identified the overexpression of c-Met/GSK3β/MYC/CCND1 oncogenic signatures that were associated with cancer progression, drug resistance, metastasis, and poor clinical outcomes in CRC." (PMID 36672275, 2023). "Moreover, multiple studies have shown that VEGFA positively regulates Wnt/β-catenin signaling through GSK-3β, which is associated with angiogenesis and cancer stemness in CRC, thus suggesting the potential autocrine action of VEGFA." (PMID 36672201, 2023). "Galectins may be associated with antiapoptotic activity and therapeutic resistance, whereas low GSK3β activity may reflect activation of Wnt signaling, two features normally associated with cancer stem cells (37, –39)." (PMID 35193955, 2022). "When the Wnt signalling pathway is activated, AKT is phosphorylated to form phosphorylated AKT with kinase activity, which can inactivate GSK-3β by phosphorylating GSK-3β to form phosphorylated GSK-3β, causing reduced degradation of intracellular β-catenin to promote apoptosis of cancer cells." (PMID 36091757, 2022). "Finally, dysregulation of Wnt3/β-catenin/GSK-3β axis is linked to a wide range of illnesses, including cancer, kidney disease, bone problems, and neurodegenerative diseases." (PMID 36015156, 2022). "However, long-term use of GSK3β antagonists and its effects on the Wtn-β catenin signalling pathway carry an unacceptable risk of developing cancer, limiting their clinical applicability." (PMID 34206637, 2021). "In several cancers, β-catenin accumulates and gets translocated to the nucleus because the β-catenin destruction complex is inhibited due to mutations in the complex’s components and inactivation of kinases such as GSK3β." (PMID 34546849, 2021). "Furthermore, the photoactivation of TMA by BL affected the canonical Wnt signalling pathway in T24 cells through modifications of the β-catenin and GSK3β expression levels, whose dysregulations are associated with several types of cancers." (PMID 33504020, 2021). "The roles of GSK-3β in cancer may differ according to the cancer type and the genetic mutations present." (PMID 33917370, 2021). "Considering the multiple roles played by CSCs in the biological hallmarks of cancer, a working hypothesis is that GSK3β is centrally involved in the underlying mechanism for sustaining CSC phenotypes." (PMID 32503133, 2020). "In addition, we describe potentially beneficial effects of GSK3β inhibition for the host and for normal cells following damage caused by conventional cancer therapy and palliative care." (PMID 32503133, 2020). "Moreover, there is increasing evidence that GSK3β inhibition protects normal cells and tissues from the harmful effects associated with conventional cancer therapies." (PMID 32503133, 2020).
cancer (continued). "Consequently, inhibition of GSK3β is a promising strategy for the prevention and treatment of harmful side effects in the central and peripheral nervous system associated with cancer therapy." (PMID 32503133, 2020). "Recently, several important studies have highlighted that NUAK1, as a key component of the antioxidant response pathway, is associated with aggressive disease and poor outcome in cancer patients through suppressing Gsk3β-dependent inhibition of NRF2 nuclear localization." (PMID 32873786, 2020). "GSK-3β functions as an important regulatory kinase and its hyperactivity have been linked to several disorders such as Alzheimer disease, schizophrenia, diabetes, and cancer." (PMID 31750236, 2019). "Loss of function in the GSK3β-Fbxw7α axis occurs in several cancer types." (PMID 30854564, 2019). "GSK3β has been implicated in several diseases including neurological disorders and cancers." (PMID 30845991, 2019). "Although PIK3CA-mutated cancer is usually sensitive to mTOR inhibition, activation of GSK3β in response to PI3K/mTOR inhibition may lead to the resistance to PI3K/mTOR inhibitors in PIK3CA-mutated cancer." (PMID 31277692, 2019). "GSK3β/β-catenin signaling pathway has been found to be associated with the pathogenesis of cancers." (PMID 31850367, 2019). "Therefore, the disruption of interphase cell cycle procession would also underlie the cancer therapeutic effect of GSK3β inhibition." (PMID 29568361, 2018). "Observed differences could be attributable to differences in the sensitivities or susceptibilities of the respective cancer cells to the same inhibitors and/or GSK3β-specific siRNA." (PMID 29568361, 2018). "GSK3β is reported to be implicated in promoting cancer invasion." (PMID 30195772, 2018). "Within cancer, GSK-3β has been linked to the process of epithelial to mesenchymal transition (EMT)." (PMID 28930226, 2017). "Aberrant GSK3β activity has been linked with several human diseases including cancer." (PMID 26498355, 2016). "Regarding the anticancer properties of IFN-γ, the implication of PI3K/PTEN/galectin-3/AKT/GSK-3β/SHP2 signaling might reflect a strategy hijacked by cancer cells to cause cellular unresponsiveness to IFN-γ." (PMID 26934444, 2016). "Although the previous study and our findings suggest that EZH2 is subjected to GSK3β control, the underlying mechanism of this regulation may differ in different cancer types." (PMID 27494834, 2016). "Increased GSK3β phosphorylation has been shown to cause rapid cancer growth." (PMID 27391337, 2016). "Compared to galectin-3-deficient cancers, galectin-3-positive cancers are correlated with the presence of inactive GSK-3β, which might facilitate the Wnt/β-catenin pathway." (PMID 26934444, 2016). "Moreover, overexpression or activation of GSK3β suppresses anchorage-independent cell growth in different types of cancer cells, whereas inactivation of GSK3β by expressing kinase deficient mutant promotes cell transformation and mammary tumorigenicity." (PMID 27494834, 2016). "However, non-core tankyrase, an enzyme that causes degradation of axin which regulates GSK3β activity, has been viewed as a molecular target for anti-cancer drug development." (PMID 26544726, 2015). "Furthermore, GSK-3β inhibition led to strongly decreased expression of several integrin types including the cancer stem cell-associated α2β1 integrin." (PMID 25344861, 2014). "To understand the mechanism that underlies involvement of GSK3β in cancer cell proliferation and resistance to therapy, we investigated the effect of GSK3β inhibition on expression and phosphorylation of proteins involved in cell cycle regulation and proliferation." (PMID 23408967, 2013). "Deregulation and signal imbalance secondary to GSK3β inhibition in cancer cells may make them more susceptible to chemotherapeutic agents." (PMID 23941783, 2013).
cancer (continued). "Furthermore, there are several reports that over-expression of WNT4 is induced by its mutated regulator genes such as beta-catenin and GSK3B or aberrant expression of miRNAs in various cancer types." (PMID 23843947, 2013). "The phosphorylation of GSK-3β decreases the susceptibility to apoptotic stresses in cancer cells." (PMID 22529978, 2012). "β-catenin is a GSK-3β target that is implicated in apoptotic resistance and survival signaling, and increased expression of β-catenin has been correlated with increased survival in cancer." (PMID 22529978, 2012). "Some proteins such as β-catenin may have mutations in the GSK-3β phosphorylation sites in certain cancer cells, which prevent GSK-3β-dependent phosphorylation and lead to constitutive activation of the Wnt/β-catenin pathway and contribute to cancer development." (PMID 33917370, 2021). "The roles of GSK-3β in cancer may differ according to cancer type and genetic mutations." (PMID 32365809, 2020). "The possible mechanism behind this may be that the phosphorylation of GSK-3β causes much more stabilization of beta-catenin, which promotes the expression of cyclin-B1 and survivin, and thereby promotes the proliferation and survival of cancer cells." (PMID 30213025, 2018). "Therefore, we investigated whether integrin β1/AKT/GSK-3β/β-catenin/TCF4/Nanog signal pathway was implicated in POSTN promoting cancer stem phenotypes of heat-exposed residual HCC cells." (PMID 28526827, 2017). "Therefore, RKIP-dependent suppression of the ERK or GSK3β pathways might be associated with the inhibitory role of RKIP in cancer metastasis." (PMID 26716415, 2016). "Despite its therapeutic importance, Lithium remains the only FDA-approved GSK3β inhibitor, underscoring the potential of IL-24 as an anti-cancer agent explored in this study." (PMID 40072085, 2025). "Briefly, GSK-3β participates in various signals, playing a central role in cancer development and progression." (PMID 41217667, 2025). "The phosphorylated AKT will further promote signal transduction through downstream effectors such as GSK3β, contributing to cancer progression." (PMID 41369408, 2025). "The current work revealed a significant downregulation of PI3K, AKT, mTOR, and GSK-3β mRNA levels in cancer cells treated with GLE and GNPs compared to the untreated group, with a significant downregulation in GNPs compared to its free counterpart." (PMID 41039321, 2025). "In contrast, our findings indicate that ArcA exhibits cancer-specific cytotoxicity and anti-metastatic activity in vitro, with GSK-3β dephosphorylation at Ser9, a process negatively regulated by MAP kinase and PI3K-AKT-mTOR signaling." (PMID 39948552, 2025). "HKDC1 promotes the stem cell properties of cancer cells by binding to glycogen synthase kinase 3β (GSK3β), which stabilizes beta-catenin." (PMID 40124623, 2025). "Future research should focus on elucidating the complex signaling networks involving GSK3β, exploring its dual roles in cancer, integrating GSK3β inhibitors into immunotherapy and developing novel, selective inhibitors." (PMID 41190025, 2025). "Both receptors also activate the GSK3β/β-catenin pathway, promoting cancer-related genes (such as c-myc, cyclin D1, and VEGF)." (PMID 40430008, 2025). "In cancer, GSK3β is a crucial component of several oncogenic signaling pathways, such as the WNT/β-catenin, Hedgehog (HH), Notch and MYC pathways." (PMID 39762409, 2025). "GSK-3β, a serine/threonine kinase factor, is essential for several signals that control important cellular functions and a variety of diseases, including cancer." (PMID 41217667, 2025).
cancer (continued). "To better understand the mechanism by which IL-24 induces apoptosis, we analyzed the role of glycogen synthase kinase-3 beta (GSK3β), a highly conserved serine/threonine kinase in cancer cells and a downstream target of PKA." (PMID 40072085, 2025). "In conclusion, understanding the temporal and cell-type-specific roles of GSK-3β will be critical for translating these findings into effective and durable cancer immunotherapies." (PMID 40649856, 2025). "Most importantly, genetic and pharmacologic inhibition of the GSK3B-53BP1 signaling axis dramatically enhances the cytotoxic response of cancer in vitro and in vivo to PARP inhibitors (PARPi) independent of BRCA1 status." (PMID 41243969, 2025). "Future studies should precisely delineate the most effective combinations of IL-24 as a GSK3β inhibitor with cytotoxic agents for prostate and other cancers." (PMID 40072085, 2025). "This paradox presents both opportunities and challenges in the therapeutic modulation of GSK-3β in cancer immunotherapy." (PMID 40649856, 2025). "Inhibiting GSK-3β has been demonstrated to boost chemotherapy sensitivity, making cancer cells more responsive to treatment, while also suppressing their growth and survival." (PMID 41217667, 2025). "Inhibiting GSK-3β has been shown to enhance the sensitivity of cancer cells to chemotherapy, making them more responsive to therapy, and to suppress their growth survival." (PMID 41217667, 2025). "For their therapeutic potential in diseases such as neurodegenerative disorders and cancer, GSK3β inhibitors have undergone extensive preclinical and clinical evaluation." (PMID 41190025, 2025). "In the context of HCC, studies have shown that GSK-3β regulates glycolysis, supplying energy to rapidly proliferating cancer cells." (PMID 40656954, 2025). "Combined inhibition of GSK3-β and Chk1 effectively inhibited cancer proliferation, both in 2D- and 3D-models, suggesting that this can be an effective strategy to inhibit cancer cell growth and survival." (PMID 41009395, 2025). "Glycogen synthase kinase-3β (GSK-3β) is a serine/threonine kinase that is currently being studied as a potential target for cancer therapies due to its important role in various critical cellular processes." (PMID 40075563, 2025). "The work reported here provides direct evidence that inhibiting GSK3β activity with IL-24 induces apoptosis in cancer cells." (PMID 40072085, 2025). "Future directions for drug development targeting GSK3β and its role in various diseases, particularly neurodegenerative disorders and cancer are promising yet complex." (PMID 41190025, 2025). "The involvement of GSK3β in cancer progression and cancers resistant to radio-, chemo-, and targeted therapy has been recognized." (PMID 40072085, 2025). "The literature has extensively documented the multifaceted and frequently paradoxical roles of GSK3β in different cancer cell types." (PMID 41153674, 2025). "This study shows, for the first time, that the molecular mechanism of the cancer-specific killing effect observed in IL-24-treated cells involves a GSK3β-dependent pathway." (PMID 40072085, 2025). "Dysregulation of GSK-3β is tissue-specific, with several cancers showing elevated expression of its active form." (PMID 39863145, 2025). "Targeting GSK3B-53BP1 axis to enhance PARPi-induced synthetic lethality of cancer cells depends on functional 53BP1." (PMID 41243969, 2025). "In fact, multiple GSK3 inhibitors have been developed, including a GSK3B inhibitor currently being tested in a phase 1/2 trial for patients with advanced cancers (NCT03678883)." (PMID 41243969, 2025). "It should be highlighted that GSK-3β is strongly expressed in many cancers, being involved in the regulation of proliferation, apoptosis, and chemoresistance." (PMID 40649990, 2025). "Previous studies have documented that AKT/GSK‐3β/Snail pathway regulates the migration and invasion of various types of cancer cells." (PMID 38545257, 2024).